HGS (hepatocyte growth factor-regulated tyrosine kinase substrate)
Description:
Involved in intracellular signal transduction mediated by cytokines and growth factors. When associated with STAM, it suppresses DNA signaling upon stimulation by IL-2 and GM-CSF. Could be a direct effector of PI3-kinase in vesicular pathway via early endosomes and may regulate trafficking to early and late endosomes by recruiting clathrin. May concentrate ubiquitinated receptors within clathrin-coated regions. Involved in down-regulation of receptor tyrosine kinase via multivesicular body (MVBs) when complexed with STAM (ESCRT-0 complex). The ESCRT-0 complex binds ubiquitin and acts as a sorting machinery that recognizes ubiquitinated receptors and transfers them to further sequential lysosomal sorting/trafficking processes. May contribute to the efficient recruitment of SMADs to the activin receptor complex. Involved in receptor recycling via its association with the CART complex, a multiprotein complex required for efficient transferrin receptor recycling but not for EGFR degradation.
Synonyms: HRS; ZFYVE8; Vps27
Tractability: Small molecule: a structure with a bound ligand is known. Antibody: UniProt places it where antibodies can reach, with high confidence. PROTAC: UniProt records ubiquitination sites on it; ubiquitination databases record sites on it; its protein half-life has been measured.
Gene: Protein-coding gene on chromosome 17 (81,683,326 to 81,703,138, forward strand). Ensembl gene ENSG00000185359.
Subcellular location: Cytoplasm; Early endosome membrane; Endosome, multivesicular body membrane
Subcellular location (Human Protein Atlas): Endosomes; Lysosomes; Cytosol
Pathways (Reactome):
Signal Transduction: EGFR downregulation; Negative regulation of MET activity; RHOBTB3 ATPase cycle; RHOU GTPase cycle
Vesicle-mediated transport: Cargo recognition for clathrin-mediated endocytosis; Clathrin-mediated endocytosis; Endosomal Sorting Complex Required For Transport (ESCRT); Lysosome Vesicle Biogenesis
Disease: Inhibition of membrane repair; InlB-mediated entry of Listeria monocytogenes into host cell; Prevention of phagosomal-lysosomal fusion
Metabolism of proteins: Ub-specific processing proteases
Gene Ontology:
Molecular function: protein binding; protein domain specific binding; ubiquitin-like protein ligase binding; ubiquitin binding; identical protein binding; metal ion binding; phosphatidylinositol binding; ubiquitin-modified protein reader activity
Biological process: membrane invagination; negative regulation of angiogenesis; negative regulation of platelet-derived growth factor receptor signaling pathway; negative regulation of receptor signaling pathway via JAK-STAT; negative regulation of vascular endothelial growth factor receptor signaling pathway; positive regulation of exosomal secretion; positive regulation of gene expression; protein localization to membrane; protein targeting to lysosome; regulation of MAP kinase activity; endocytic recycling; endosomal transport; macroautophagy; membrane fission; multivesicular body assembly; negative regulation of cell population proliferation; protein transport to vacuole involved in ubiquitin-dependent protein catabolic process via the multivesicular body sorting pathway; receptor internalization; regulation of protein catabolic process; signal transduction
Cellular component: cytosol; early endosome; early endosome membrane; endosome; ESCRT-0 complex; extracellular exosome; cytoplasm; phagocytic vesicle lumen; multivesicular body membrane
Genetic constraint (gnomAD): Loss-of-function variants: 64 observed, 101.05 expected, observed/expected ratio (o/e) 0.63, 90% interval 0.52 to 0.78. The synonymous counts are far from expectation, so gnomAD's model fits this gene poorly and the ratio says little. Missense variants: 994 observed, 1,020.4 expected, observed/expected ratio (o/e) 0.97, 90% interval 0.92 to 1.03. Synonymous variants: 546 observed, 422.59 expected, observed/expected ratio (o/e) 1.29, 90% interval 1.2 to 1.39.
Homologues: Orthologues: chimpanzee HGS (99% identical), mouse Hgs (93% identical), guinea pig HGS (93% identical), rat Hgs (93% identical), macaque HGS (93% identical), dog HGS (89% identical), tropical clawed frog hgs (79% identical), zebrafish hgs (78% identical), pig HGS (70% identical), Drosophila melanogaster Hrs (44% identical), Caenorhabditis elegans hgrs-1 (37% identical). Paralogues in human: STAM (19% identical), STAM2 (18% identical), TOM1L2 (15% identical), TOM1 (14% identical), GGA3 (12% identical), GGA1 (12% identical), GGA2 (11% identical), TOM1L1 (11% identical), WDFY1 (6% identical), WDFY2 (5% identical).
Diseases named in the same sentence as HGS in open-access papers:
HGS is named in the same sentence as 23 diseases in open-access papers, as found by Europe PMC text mining. Sharing a sentence is not in itself a finding about the gene and the disease. The quoted sentences say what the papers report.
colorectal cancer (5 papers, 2015 to 2025). A primary or metastatic malignant neoplasm that affects the colon or rectum. "Clinically, low HGS expression is positively correlated with the malignancy of colorectal cancer." (PMID 39766882, 2024). "The overexpression of HGS in mouse melanoma B16 cells and human colorectal cancer COLO205 cells promoted cancer characteristic anchorage-independent cell growth ability and tumor growth, whereas the overexpression of the coiled-coil domain of HGS in these cells suppressed them." (PMID 39859488, 2025).
melanoma (5 papers, 2016 to 2025). A malignant, usually aggressive tumor composed of atypical, neoplastic melanocytes. "The HGS protein was overexpressed in multiple tumors of different origins (stomach, colon, liver, cervix and melanoma) based on very limited clinical specimens." (PMID 27312428, 2016).
liver cancer (4 papers, 2015 to 2024). An epithelial or non-epithelial malignant neoplasm that arises from the liver. "The depletion of HGS reduced cell growth and induced apoptosis in liver cancer cells via β-catenin." (PMID 39199296, 2024). "Moreover, the O-GlcNAcylation of HGS has been shown to enhance tumor growth in mice and to increase chemoresistance in liver cancer cells." (PMID 39199296, 2024). "Our protein data further confirm that β-catenin and E-cadherin may be a tumor suppressor, while HGS may be an oncogene in liver cancer." (PMID 29042578, 2017). "As β-catenin activity was modulated by decorin while HGS has been shown to be required for survival in β-catenin activated background, the role of β-defensin 1 plays in β-catenin-mediated liver cancer development with this decorin- β-catenin-HGS axis warrant further confirmation and investigation." (PMID 29042578, 2017). "Thus, our findings strongly suggest the existence of a SL interaction between HGS and oncogenic CTNNB1 in HuH6 and HCT116 cells; nonetheless, further investigation is required to validate HGS as a new therapeutic target for liver cancers with CTNNB1 mutations." (PMID 26715116, 2015). "Furthermore, the downregulation of β-defensin 1 and E-cadherin, and upregulation of hepatocyte growth factor-regulated tyrosine kinase substrate, were further confirmed in liver cancer and adjacent normal tissue collected from in-house Chinese liver cancer patients." (PMID 29042578, 2017). "One of these genes (HGS) is an SL partner of oncogenic β-catenin in colorectal HCT116 cancer cells, suggesting that the LS interaction between HGS and CTNNB1 is not limited to liver cancer." (PMID 26715116, 2015).
cardiomyopathy (1 paper, 2022). A disease of the heart muscle or myocardium proper. "In this study, we demonstrated that loss of HGS in cardiomyocytes led to RCM-like cardiomyopathy in mice, indicating that HGS may be a causative gene for RCM." (PMID 35342336, 2022).
colon cancer (1 paper, 2016). "However, in all cases, HGS mRNA is an unfavorable prediction factor in colon cancer." (PMID 27312428, 2016).
glioma (1 paper, 2021). A benign or malignant brain and spinal cord tumor that arises from glial cells (astrocytes, oligodendrocytes, ependymal cells). "For example, in gliomas relative to normal brains, miR-296 is elevated in endothelial cells and directly targets hepatocyte growth factor-regulated tyrosine kinase substrate (HGS)." (PMID 34803608, 2021).
hepatoma (1 paper, 2015). "Taken together, despite the fact that the HGS effect may slightly vary in different hepatoma cell lines, HGS is required for the secretion of naked capsids." (PMID 26431433, 2015).
hereditary neuralgic amyotrophy (1 paper, 2015). "Mutations in Septin 9 have been found in many, but not all, cases of hereditary neuralgic amyotrophy, making HGS a good candidate gene for other cases of this disease." (PMID 26115514, 2015).
memory impairment (1 paper, 2021). "The HGS gene ASNSD1 is involved in asparagine biosynthesis and its expression is decreased in our patients with severe memory impairment." (PMID 33986407, 2021). "Finally, three HGS genes, VLDR, FGFR2, and HBEGF, that are involved in synaptic plasticity and memory formation and belong to the red module—which is correlated with E-onset and memory impairment-showed significantly decreased expression in early disease onset patients." (PMID 33986407, 2021).
thyroid disease (1 paper, 2022). "No previous association with thyroid disease has been reported for the remaining five proteins: sialic acid acetylesterase (SIAE), hepatocyte growth factor-regulated tyrosine kinase substrate (HGS), Myotrophin (MTPN), 60S ribosomal protein L24 (RPL24), and Coronin-7 (CORO7)." (PMID 36068205, 2022).
tubular adenoma (1 paper, 2016). A usually polypoid neoplasm arising from the glandular epithelium. "The upregulation of HGS in the CRC tumor tissues was significant compared with the adjacent non-tumor, tubular adenoma and normal colorectal tissues (all P < 0.0001)." (PMID 27312428, 2016).
tumor (14 papers, 2014 to 2025). "HGS, the hepatocyte growth factor-regulated tyrosine kinase substrate, has been implicated in tumor growth and metastasis and over-expression of HGS prevents the degradation of the EGF receptor." (PMID 25416589, 2014). "Moreover, high levels of HGS protein were associated with worse tumor biological behavior, such as worse differentiation, a larger tumor size and poor prognosis." (PMID 27312428, 2016). "Immunohistochemistry results showed that EPS15L1 and HGS were strongly expressed in tumor tissues and slightly expressed in normal tissues, and semi-quantitative analysis showed significant difference." (PMID 41216288, 2025). "While researchers previously demonstrated that HGS depletion inhibits tumor metastasis by upregulating E-cadherin, our study not only confirms HGS’s critical role in CM metastasis but further reveals its potential novel mechanism in regulating M2 macrophage polarization through the ESCRT complex." (PMID 41216288, 2025). "The downregulation of miR-296-5p in PC tissues has been linked to the overexpression of its target, Hepatocyte Growth Factor-Regulated Tyrosine Kinase Substrate (HGS), which promotes tumor cell invasiveness and metastasis by downregulating E-cadherin and disrupting epithelial integrity." (PMID 41210508, 2025). "Therefore, HGS may participate in tumor progression via the regulation of the component of tumor microenvironment." (PMID 27312428, 2016). "Low-molecular-weight compounds that inhibit the dimerization of HGS/C and STAM/C, such as HGS/C and OP12-462, are expected to exhibit tumor growth inhibitory effects." (PMID 39859488, 2025). "Evident by comparison to their cognate normal tissue analogs, discernible upregulation was registered across a slew of tumor tissues for PPIA, TRAF2, TRIM28, and HGS." (PMID 38460947, 2024). "Phosphorylation of hepatocyte growth factor-regulated tyrosine kinase substrate (HRS), a pivotal component of the ESCRT-0 complex, restricts tumor infiltration of cytolytic CD8+ T-cells, regulating anti-tumor immunity by inducing PD-L1+ immunosuppressive exosomes." (PMID 36704194, 2022).
cancer (8 papers, 2012 to 2025). A tumor composed of atypical neoplastic, often pleomorphic cells that invade other tissues. "The decreased expression of VEGF-A and the overexpression of hepatocyte growth factor-regulated tyrosine kinase substrate (HGS) in the cancerous tissue confirmed that the angiogenetic pathway is involved in exercise-induced benefits against cancer progression." (PMID 35454797, 2022). "HGS and its receptor tyrosine kinase MET have a role in uncontrolled cell survival, growth, and angiogenesis in cancer." (PMID 37266401, 2023). "Also, HGS and other components of the endosomal sorting complex required for transport (ESCRT) machinery are misregulated in various cancers." (PMID 22796207, 2012).
HGS also shares sentences with these, for which no sentence is quoted: prostate carcinoma (2 papers); breast carcinoma (1); depression (1); Hypertension (1); infection (1); liver fibrosis (1); parathyroid tumors (1); prostate tumor (1); thyroid cancer (1); thyroid nodule (1).